IL5 (interleukin 5)
Diseases named in the same sentence as IL5 in open-access papers (continued):
Sharing a sentence is not in itself a finding about the gene and the disease.
eosinophilia (continued). "In a recently published phase 2a trial, inhaled SB010 statistically significantly attenuated asthmatic responses after allergen challenge in patients with allergic asthma and decreased the Th2-mediated inflammatory profile including blood interleukin-5 and sputum eosinophilia." (PMID 29615049, 2018). "Furthermore, HDM-treated C57BL/6Mthfr-/- mice compared to HDM-treated C57BL/6 mice have reduced whole lung lavage (WLL) cellularity, eosinophilia, and Il-4/Il-5 cytokine concentrations." (PMID 29329322, 2018). "Amongst physiological mediators promoting eosinophil localization within adipose tissue, locally IL-5 released by innate lymphoid type 2 cells (ILC2s), as well as extracellular matrix molecules, emerged as chief regulators of adipose tissue eosinophilia development and survival." (PMID 30298073, 2018). "Although the efficacy of mAbs towards IL-5 is indisputable in eosinophilic asthma, as reported in several studies, the clinical results are more evident in those patients with a high percentage of blood and sputum eosinophilia." (PMID 29879991, 2018). "Whether residual tissue eosinophilia accounts for some of the disappointing clinical responses observed with anti-IL-5 treatment remains unknown." (PMID 29682504, 2018). "Studies indicate an increased effect of anti-IL5 the higher the eosinophilia." (PMID 29535852, 2018). "Bronchial eosinophilia may persist even when peripheral blood eosinophil count has been reduced by anti-IL-5 treatment." (PMID 30498762, 2018). "Interestingly, biologics targeting IL-5 have been largely unsuccessful in alleviating clinical symptoms despite their success in achieving substantial reductions in tissue eosinophilia." (PMID 30524424, 2018). "The induction of eosinophilia and goblet cell metaplasia depends on IL‐5 and IL‐13, respectively." (PMID 29444897, 2018). "This phenomenon may contribute to rebound eosinophilia and/or disease worsening with anti-IL-5 treatment." (PMID 29682504, 2018). "Also, tissue IL-5 and eosinophilia at the site of larval establishment have been demonstrated in experimental human challenge models." (PMID 29547639, 2018). "Similarly, ST2 + IL-5+ HPC numbers were increased in the sputum of COPD patients with airway eosinophilia (p < 0.001)." (PMID 29859068, 2018). "Thus, “increased incidence” of neutrophilia or eosinophilia (or elevated IL-5, etc.)is a more accurate representation of these phenotypic groups than the common description that each is “characterized” by Th1/neutrophilic or Th2/eosinophilic inflammation." (PMID 30283438, 2018). "In addition, IL-33 stimulates type 2 innate lymphoid cells to produce IL-5 and -13 resulting in eosinophilia and goblet cell hyperplasia, respectively." (PMID 30176857, 2018). "It has also been reported that the CCL20/CCR6 system may play a pivotal role in allergic airway responses such as AHR, airway eosinophilia, and production of IL-5 and IgE." (PMID 28628664, 2017). "Neither Th2 cytokines nor the transcription factor GATA3 as well as features triggered by IL-4 (IgG1 antibodies, RELM-ß) or IL-5 (eosinophilia) could be detected in co-infected animals." (PMID 28791259, 2017). "Eosinophilic bronchitis is usually a Type 2 (T2)-driven process and therefore a sputum eosinophilia of greater than 3% usually indicates a response to treatment with corticosteroids or novel therapies directed against T2 cytokines such as IL-4, IL-5, and IL-13." (PMID 29018800, 2017). "In addition to IL-5, cytokine IL-3 and GM-CSF have also been shown to mediate airway eosinophilia and AHR." (PMID 28106744, 2017). "However, if ovaries are removed 1 day before sensitization to OVA, lung eosinophilia and IL-5 levels are increased." (PMID 28959241, 2017). "Progesterone increased IL-5 levels and elevated airway eosinophilia." (PMID 28076614, 2017).
eosinophilia (continued). "Such a mechanism may explain the protective effect of parasite infection in patients with multiple sclerosis where eosinophilia is induced by IL-5, produced by the immune response to parasites." (PMID 29163523, 2017). "In this study, we examined if the effects of parasitic infection could be due to increased IL-5, which not only induce eosinophilia but also as a bystander effect further expands antigen-specific CD4+CD25+ Treg activated by autoantigen and IL-4." (PMID 29163523, 2017). "Eosinophil infiltration and peripheral eosinophilia are dependent on the eosinophil-specific cytokine (IL-5) and chemokines (eotaxin and RANTES), which provoke an eosinophilic response in the peripheral blood and airways via the C-C chemokine receptor type 3 (CCR3)." (PMID 29062168, 2017). "Instead, as recently determined by Fulkerson and colleagues, an alternative IL-5-independent pathway for promoting eosinophilia might be in place." (PMID 27882241, 2016). "In addition, airway YKL-40 level increases in human allergen challenge and murine models implicate YKL-40 in airway eosinophilia and IL-5 production." (PMID 26851968, 2016). "IL-5 regulates eosinophil functions (development, activation, migration, survival) and, together with eotaxin, is a critical molecular switch for the induction of blood and tissue eosinophilia." (PMID 27297409, 2016). "IL-5 is involved with eosinophilia and plays an essential role in allergic inflammation." (PMID 25973430, 2015). "Taken together, lower TGF-β1 levels in lungs with NP-CpG may be a consequence of lower eosinophilia and Th2-related cytokine production (IL-4, IL-5, IL-13) in NP-CpG treated mice." (PMID 26387548, 2015). "IL-5 is best characterized for eosinophilia that dominates airway inflammation on allergic asthma." (PMID 26064160, 2015). "The reduction in BAL eosinophilia in the Ccsp-creTgfb1−/− mice was probably due to reduced eosinophil trafficking to the airways because lower levels of the key eosinophil chemoattractant eotaxin-2 and also IL-5 were detected in the BAL." (PMID 26588780, 2015). "In 1996, a study reported that ‘IL-5 deficient’ mice failed to develop the characteristic eosinophilia and airway hyper-reactivity after ovalbumin-sensitization." (PMID 25709744, 2014). "However, mice sensitized using the moderate dose of 10–1 μg LPS and challenged with OVA six times had markedly less IL-5 and eosinophilia in BALF and lower AHR after six challenges than mice sensitized using lower amounts of LPS." (PMID 24168764, 2014). "Pre-treatment with parasite-derived exosomes before Alternaria extract administration led to a sharp reduction in bronchoalveolar lavage eosinophilia, and suppressed expression of the Type 2 cytokines interleukin (IL)-5 and IL-13 by innate lymphoid cells (ILCs)." (PMID 25421927, 2014). "In addition to the eosinophil chemotactic factors IL-3 and GM-CSF, IL-5 is a major soluble factor for mediating eosinophilia." (PMID 25273521, 2014). "In addition, closer analyses of the available data indicate alternative mechanisms of tissue eosinophilia that remain uncurbed with the current dosage and delivery platform of the anti-IL5 molecules." (PMID 25709744, 2014). "Priming in vivo for an increased ex vivo response to the eosinophil-selective growth and differentiation factor, interleukin (IL)-5, is an important component of the hematological response to allergen challenge, which parallels in vivo eosinophilia but is independently regulated." (PMID 25477712, 2014). "Subcutaneous administration of IL-5 induces a concentration-dependent eosinophilia in mice." (PMID 23378838, 2013). "Dysregulated type 2 immunity in allergic asthma is characterized by an expansion of CD4+ Th2 cells and cytokines (IL-4, IL-5, IL-13), elevated total and allergen-specific IgE, eosinophilia, and airway inflammation and a counterbalance emergence of B1a cells with regulatory capacity." (PMID 23840604, 2013).
eosinophilia (continued). "The stronger increase in ILC2 numbers in the absence of IL-1β following Hp infection could be confirmed by pharmacological blockade with Anakinra, and Anakinra treated mice additionally exhibited increased eosinophilia and IL-5 and IL-13 cytokine levels." (PMID 23935505, 2013). "Tissue eosinophilia could only be restored in these mice by administration of intravenous IL-5 for 72 h." (PMID 23378838, 2013). "Therefore, because of the reduction in nasal mucosa eosinophilia, IL-4 and IL-5 levels in NLF, and OVA-specific IgE levels in sera, 2ME2 treatment likely inhibits the nasal allergic responses." (PMID 23133644, 2012). "As a result, the predominance of T helper-2 subset of T helper cells and the consequential increase in IL-5 cytokines accompanying peripheral eosinophilia and high serum IgE levels may be blamed for the development of EP in patients who are HIV positive." (PMID 23148793, 2012). "Indeed adding CpG to our N+LT neonatal vaccine not only reduced the Th2 bias of the recall response to a boost with N (less IL-5, more IgG2a), but also abrogated eosinophilia following an RSV challenge, as assessed in BAL cells." (PMID 22655066, 2012). "Thus, in the absence of UVR-induced increases in serum 25(OH)D3 in the male vitamin D3-deficient mice, UVR significantly suppressed T helper type-2-specific responses (eosinophilia and IL-5 in lavage fluid) in this model of allergic airway disease." (PMID 23049920, 2012). "The increase in IL-5 and IL-4 may be responsible for the possible eosinophilia and elevation of serum immunoglobulin E levels, respectively, in HIV-related eosinophilic diseases like eosinophilic folliculitis and EP." (PMID 23148793, 2012). "Increased IL-10 levels could explain the reported reductions in IL-4 and IL-5 as well as the inhibition of eosinophilia, since IL-10 has been shown to downregulate IL-4 and IL-5 expression by Th2 cells and reduce eosinophil survival." (PMID 22966222, 2012). "Anti-IL-5 treatment also reduced the disposition of extracellular matrix proteins in bronchial biopsies obtained from atopic asthmatic patients, suggesting that neutralizing IL-5 minimizes the repair process following airway injury and eosinophilia." (PMID 22405472, 2012). "We hypothesised that CF prevents AHR by downregulating IL-5 production and thereby reducing eosinophilia." (PMID 22439901, 2012). "We hypothesize that MA and MA128 and CsA prevent AHR by downregulating eotaxin, IL-5 and IL-13 expression and, in so doing, by reducing eosinophilia." (PMID 22203879, 2012). "We hypothesized that HPN and formoterol prevent AHR by downregulating eotaxin and IL-5 expression and, in so doing, by reducing eosinophilia." (PMID 21772663, 2011). "Overall, we believe that the patient may have had a variant of a lymphocytic hypereosinophilic syndrome given the systemic eosinophilia, modestly high levels of sputum IL-5 and serum TARC and raised serum total IgE early in the course of the disease." (PMID 21362188, 2011). "IL-5 and CCL11 cooperate to generate an intestinal eosinophilia in a model of gastrointestinal allergy; here, initial eosinophil release from the bone marrow appears to be mediated by IL-5, whereas local production of CCL11 in the intestine mediates the recruitment from the blood to the intestine." (PMID 21155838, 2011). "Therefore, therapeutic strategies that inhibit eosinophilia in eosinophil-mediated diseases should consider both pathways, even though both pathways are critically dependent on IL-5." (PMID 21423619, 2011). "Taken together, the observed reduction in airway eosinophilia by artesunate may be a result of combined inhibitory effects on IL-4, IL-5, IL-13, eotaxin and RANTES production, and on adhesion molecule expression, secondary to inhibition of PI3K/Akt." (PMID 21695271, 2011). "It has been suggested that IL-5 and eotaxin may collaborate in the regulation of blood and tissue eosinophilia in mice." (PMID 21772663, 2011).
eosinophilia (continued). "Giving an antibody to block interleukin-5, a regulator of eosinophilopoiesis, eosinophil migration, and eosinophil survival, eliminated both blood and airway lumen eosinophilia but had little effect on airway wall eosinophils, and no pro-apoptotic effect has been demonstrated." (PMID 20540713, 2010). "In addition to the suppression of airway eosinophilia and local IL-5 and eotaxin secretions, airway pathology was also attenuated." (PMID 20306466, 2010). "Allergic asthma is caused primarily by an inappropriate CD4+ Th2 response, which results in symptoms mediated by Th2 cytokines, including IL-13 provoking airways hyperresponsiveness and mucus production, IL-4 promoting the production of antigen specific IgE, and IL-5 inducing eosinophilia." (PMID 20659336, 2010). "Alternatively, interleukin-5 antibodies such as mepalizumab might be useful if repeat vaccinations are being performed at the same site and compartment, by controlling tissue eosinophilia and directly interfering with Th2 cytokine activity." (PMID 20727190, 2010). "Eosinophilia is driven by Th2 cytokines (e.g., IL-4, IL-5, IL-13) produced by Th2 cells." (PMID 19657453, 2009). "In addition, in a subset of patients with HES, eosinophilia is secondary to a primitive Th2 lymphoid disorder, overproducing interleukin-5 (IL-5), indicating the existence of lymphocyte-mediated HES." (PMID 19187542, 2009). "It was shown that stimulated peripheral blood mono-nuclear cells from patients with CSS secrete significantly increased amounts of interleukin 5 (IL-5) compared with healthy controls, suggesting that IL-5 contributes substantially to the development of eosinophilia in CSS." (PMID 23283308, 2008). "Further, long term challenges led to prolonged and intense airway inflammation with marked lymphocytosis, but moderate eosinophilia, sustained IL-5 production and ovalbumin-specific IgG2a antibodies, the latter suggesting a Th1 component to the immune response." (PMID 18253511, 2008). "IL-5 is an important mediator of eosinophilia in mice with parasite infections." (PMID 16889674, 2006). "The research involving tissue factors, such as granulocyte macrophage colonies stimulating factor (GM-CSF) and interleukin 5 (IL-5), leads to the mechanisms involved in the maintenance of eosinophilia, which is essential for the pathogenesis on eosinophilic nasal polyps." (PMID 16446960, 2005). "Perhaps this low rate is explained by the chronicity of the disease with eosinophilia being present only early in the course via stimulation of Th2 lymphocytes and production of IL-4 and IL-5 subsequently generating IgG1 and IgE-secreting cells, and eliciting eosinophilia." (PMID 15904502, 2005). "The results show that the infection of animals with Toxocara canis induced an early increase in serum IL-5 levels that might be essential for eosinophil differentiation and proliferation and for the development of eosinophilia." (PMID 18475693, 1996). "This distinct mechanism sets benralizumab apart from other anti-IL-5 agents, enabling effective eosinophil depletion and suppression of eosinophilic inflammation, a response clearly observed in our case through the rapid and sustained resolution of both eosinophilia and clinical manifestations." (PMID 40943043, 2025). "Anti-IL5 may have a role in those rare refractory cases with persistent eosinophilia." (PMID 40115529, 2025). "Type 2 inflammation is associated to a greater disease burden and is defined by tissue eosinophilia (≥ 10 eosinophils/high field power, blood eosinophilia (≥ 150 cells/μL and high level of serum total IgE (≥ 100 KU/L) and additional increased expression of T2 cytokines such as IL-4, IL-5, IL-13." (PMID 38913122, 2024). "Eosinophils have been noted to have an important role in the pathobiology of HL. ​The mechanism of eosinophilia remains unknown, though various mediators like interleukin 5 (IL-5) and granulocyte-macrophage colony-stimulating factor (GM-CSF) have been implicated​." (PMID 39723308, 2024).
eosinophilia (continued). "Indeed, we found that both eosinophilia and eosinophil activation, as well as circulating IL-5 levels, increased during treatment and dropped to below baseline six months thereafter, in line with several treatment studies in endemic and non-endemic populations." (PMID 38771861, 2024). "It is important to highlight that these models have systemic changes in eosinophil counts through their lifespan and might have stronger phenotypes than when inducing hyper eosinophilia with IL-5 injection, or when reducing their number with blocking antibody for IL-5." (PMID 38585275, 2024). "Furthermore, IL-5-dependent eosinophilia in BALF was reduced in GITR-KO mice." (PMID 38540714, 2024). "Additionally, IL-5, which is associated with eosinophilia and VLS induced by high-dose IL-2, did not significantly change in response to SAR’245 treatment alone or in combination with pembrolizumab or nivolumab." (PMID 39320047, 2024). "Since our data suggest that, in these patients, persistent eosinophilia was unrelated to IL-5 pathway triggered by allergen exposure, we hypothesized that a drug able to determine complete eosinophil depletion could be more appropriate than a drug able to modulate IL-5 pathway (see the Section 4)." (PMID 38337448, 2024). "It is thus interesting to hypothesize that increased eosinophil counts are either a biomarker for a Th2-mediated graft rejection and/or damaged lung graft epithelial cells, which by secreting IL-33 promote IL-5-expressing ILC2s, eventually inducing eosinophilia." (PMID 36984489, 2023). "Therefore, to establish that rIL-18 indeed transform in vivo IL-5 generated naïve eosinophils to pathogenic eosinophils; therefore, we used CD2-IL-5 mice that do not have intraepithelial eosinophilia and degranulated eosinophils." (PMID 37524769, 2023). "Indeed, L.rhamnosus supplementation inhibited the lung eosinophilia (with no impact on neutrophil and lymphocyte numbers) and the Th2-associated mRNA transcripts (i.e., Il4 and Il5 and a trend for Il13) in mice neonatally sensitized with OVA." (PMID 36685549, 2022). "IL-5, IL-17 and IL-23 inhibitors may be effective given their roles in promoting eosinophilia." (PMID 36405625, 2022). "Interestingly, L.rhamnosus maternal supplementation resulted in decreased eosinophilia and neutrophilia in the bronchoalveolar lavage (BAL) fluid and in decreased Th2-associated cytokines mRNA transcripts (i.e., Il4, Il5 and Il13) in the lung of neonatally sensitized mice." (PMID 36685549, 2022). "Similarly, TH2-cytokines lead to increased IL-5 production which can lead to eosinophilia." (PMID 34712855, 2021). "However, the eosinophils that did develop in IL-5–deficient mice were morphologically similar to eosinophils in control mice, but IL-5–deficient mice failed to develop blood and tissue eosinophilia in response to helminth infection." (PMID 33335529, 2020). "Besides, our synbiotic, TP, and LGG strongly down-regulated eosinophilia, IL-5, CCL17, IL-13." (PMID 32582180, 2020). "Interestingly, however, IL-5 over-expression alone appears to be insufficient for induction of eosinophil-mediated damage, as evidenced in IL-5 transgenic mice that have marked eosinophilia in blood and certain tissues, without associated organ dysfunction." (PMID 29682504, 2018). "Patients with lymphocyte-variant primary eosinophilia have no overt haematological malignancy, but their haematopoiesis is characterised by occult expansion of immunophenotypically aberrant T lymphocytes, which produce cytokines such as IL5." (PMID 29619379, 2018). "The eosinophilia observed in this cohort was most likely a response to F. hepatica rather than nematode infection, particularly since there was a significant positive relationship between fluke Ab PP values and both peripheral eosinophil counts and SomAg-stimulated IL-5 transcription." (PMID 28993458, 2018).